PREX1 (phosphatidylinositol-3,4,5-trisphosphate dependent Rac exchange factor 1)
Diseases named in the same sentence as PREX1 in open-access papers (continued):
Sharing a sentence is not in itself a finding about the gene and the disease.
cancer (continued). "To look for genetic alterations that might be linked to increased PREX1 expression, we first compared the frequency of the top ten mutant genes in LGG, LAML, KIRC, and LUAD; those cancer types that had statistical significance of PREX1 expression and patient survival." (PMID 35875157, 2022). "PREX1 and CSE1L have been well demonstrated to involve in phosphoinositide AKT signaling pathway and promote cancer progression." (PMID 37749132, 2023). "However, several small-molecule inhibitors that target the interface between PREX1/PREX2 and Rac, such as NSC23766 and PREX2-in 1, have been developed and shown preclinical efficacy in other cancers 44-46." (PMID 40365293, 2025). "PREX1 ranked among the most significantly more accessible genes in older adults, coding for the guanine-nucleotide exchange factor (GEF) for RAC1, which is known to function in cancer cell proliferation and metastasis." (PMID 38329813, 2024). "A fraction of PREX1 signaling partners exhibited good correlation with astrocyte and microglia markers and negative expression in cancer stem cells and oligodendrocytes (left side)." (PMID 35875157, 2022). "In addition, NSCLC subgroups with higher nodal metastasis levels or cancer stages generally have lower median expression of ABR, PREX1, DOCK2, and DOCK4, whereas statistical significance for the comparison among these subgroups remains to be verified with a larger number of samples." (PMID 34783629, 2021). "Hence, the downregulation of ABR, PREX1, DOCK2, and DOCK4 promotes cancer development and leads to a poor prognosis by activating MYC and DNA repair signaling pathways in NSCLC, and further in vitro and in vivo studies are necessary to further confirm their association." (PMID 34783629, 2021). "Here we identified specific CpG sites in L3MBTL1, NKX6-2, PREX1, TRAF7, PRDM14,and NEFM as primarily methylated in cancer specimens but not in other colonic lesions; these genes were also found to be implicated in many important pathways relevant to neoplastic transformation." (PMID 27688749, 2016).
tumor (30 papers, 2011 to 2025). "In PREX1, another known tumor suppressor, we found two variants (p.R1243W and p.V569M) in cases with MSS CRC at 55 and 50 years." (PMID 29212164, 2017). "A remarkably higher level of PREX1 was found in patients with worse M- and N-stage, disclosing its promoting role on tumor metastasis." (PMID 38903921, 2024). "Consistently, PREX1 was downregulated in the NGF/NGFR low‐expression tumor tissues of HCC patients and also in the NGF and NGFR low‐expression co‐culture system." (PMID 38204220, 2024). "TIMER was employed to investigate the expression of PREX1 between tumor and normal tissues in multiple cancers." (PMID 38903921, 2024). "Overall, we have completed a comprehensive evaluation of PREX1, uncovering that it plays a critical role in tumor immune environment and serves as an indicator for dismal prognosis in LIHC patients." (PMID 38903921, 2024). "As PREX1 played a critical role in LIHC tumor progression, we analyzed the expression of PREX1 in LIHC cell lines." (PMID 38903921, 2024). "NGF‐NGFR communication inefficiency suppressed mitotic spindle formation via HDAC1 unclear trans‐localization‐inhibited PREX1 expression, thereby suppressing the proliferation of T cells that had infiltrated into the tumor tissues of HCC patients." (PMID 38204220, 2024). "KALRN, MCF2/Dbl, NGEF/EPHEXIN, ARHGEF7/βPix/COOL-1, CDC42EP2, DOCK9, NET1, TIAM2, ABR, PLEKHG5, RhoBTB2 and PREX1 were identified as being increased at the tumour rim." (PMID 33256106, 2020). "Although several proteins (e.g., ACVRL1, DUSP4, PREX1) showed increased expression in the high-risk group, PD-L1 and p38 MAPK were prioritized for mechanistic validation due to their established roles in tumor-immune interactions." (PMID 41050683, 2025). "In this study, we found that PREX1 played a vital role in tumor progression in LIHC." (PMID 38903921, 2024). "This study informed that PREX1 may have a fundamental role in tumor immunity of LIHC, but limitations still remain." (PMID 38903921, 2024). "Considering the complexity of immune regulation, PREX1 may be involved in various signaling pathways and regulatory networks that are decisive for tumor development." (PMID 38903921, 2024). "The first row indicates that PREX1 was expressed in most cells of the tumor microenvironment." (PMID 35875157, 2022). "However, the roles of transglutaminase, PREX1, and caspase-7 in tumor immunity are rarely studied, and further investigation would be valuable." (PMID 34177954, 2021). "PREX1 activates insulin growth factor 1 receptor/insulin receptor signaling, as well as Rac1, phosphoinositide 3 kinase/protein kinase B, and mitogen-activated and extracellular-regulated kinase signaling, and PREX1 promotes cell and tumor viability." (PMID 32629428, 2020). "Thus, the fact that tumor-promoting and metastatic genes such as PREX1 can be reactivated by demethylating agents poses a serious therapeutic challenge, specially taking into account that PREX1 demethylation is correlated with poor prognosis." (PMID 25248717, 2014). "Thus, PREX1 is an important tumor promoter in LIHC development in vitro." (PMID 38903921, 2024). "To investigate the potential roles of PREX1, CSE1L and STAU1 in CRC pathogenesis, we first compared the expression of these three genes in tumor and adjacent normal tissues in GEO and our own CRC tissues." (PMID 37749132, 2023). "Results showed that PREX1, CSE1L and STAU1 were significantly overexpressed in tumor tissues than in normal tissues in both cohorts." (PMID 37749132, 2023). "The downregulation of PREX1 and DOCK2 were significantly correlated with earlier tumor progression in LUSC and LUAD patients." (PMID 34783629, 2021). "Additionally, the major effector of PREX1 protein activity is related to the induction of actin-mediated membrane ruffling and lamellipodia production at the leading edge of cell migration, and abnormally activated Rac is involved in the metastasis and invasion of tumor cells." (PMID 33652974, 2021).
tumor (continued). "Interestingly, the group within overexpression of three genes PREX1, CSE1L and STAU1 presented a largest tumor volume among all tested groups." (PMID 37749132, 2023). "Similarly, H&E staining and immunohistochemical analysis (Ki67, PREX1, CSE1L and STAU1) also support the synergistic effect of three genes on tumor growth." (PMID 37749132, 2023). "In addition to analyzing the tumor-suppressive effects of ABR, PREX1, DOCK2, and DOCK4 through bioinformatics, we further verified the role of ABR in proliferation, migration, and cloning ability in PC9 and H1703 cells experimentally." (PMID 34783629, 2021). "In contrast, several proteins, including PREX1, LCK, PD-L1, transglutaminase, and cleaved caspase 7, were elevated in the CHIM subgroup, which might be predictors of “hot tumor”." (PMID 34177954, 2021). "In CRC, the expression of ADAR1 and HER3 increased while PREX1 levels decreased with stage progression from I to IV; thus, we observed a positive correlation between ADAR1 and HER3 and a negative correlation between PREX1 and the tumour stage of CRC." (PMID 37189448, 2023).
PREX1 also shares sentences with these, for which no sentence is quoted: Alzheimer disease (2 papers); breast tumors (2); diabetes (2); fibrosis (2); lymphoma (2); ovarian carcinoma (2); type 2 diabetes (2); amyotrophic lateral sclerosis (1); atherosclerosis (1); bladder urothelial carcinoma (1); brain tumor (1); chronic myeloid leukemia (1); endometrial cancer (1); hepatocellular carcinoma (1); hypertensive disorder (1); Insulin resistance (1); kidney damage (1); lung adenocarcinoma (1); metastatic prostate carcinoma (1); neuroblastic tumor (1); neuroblastoma (1); oral cancer (1); oral squamous cell carcinoma (1); Parkinson disease (1); preeclampsia (1); schizophrenia (1); skin cancer (1); uveal melanoma (1); vascular tumors (1).